MTOR (mechanistic target of rapamycin kinase)
Diseases named in the same sentence as MTOR in open-access papers (continued):
Sharing a sentence is not in itself a finding about the gene and the disease.
autism (continued). "Dysregulation of the mTOR/eIF4E axis disrupts the clock and engenders ASD-like phenotypes in animals, indicating potential crosstalk between the brain clock and autism." (PMID 34943821, 2021). "Higher activity of mTOR, ERK, and p70S6 kinase and lower activity of GSK3α and tuberin (TSC2) have been observed in cells from children with non-syndromic autism that suggests an increased Akt/mTOR pathway activity in idiopathic ASD." (PMID 31847491, 2019). "Studies are needed that directly compared autism and schizophrenia with regard to neuronal PI3K-Akt-mTOR activity and its effects on neuronal survival, protein synthesis levels and patterns, synaptic plasticity and dendritic spine phenotypes." (PMID 31548888, 2019). "This study identifies differential expression of mTOR and MAPK pathways in patients affected by mild and severe idiopathic autism." (PMID 30705255, 2019). "Mutations in the eIF4E promoter are present in some individuals with autism, and eIF4EBP2 knockout and eIF4E-overexpressing mice exhibit autism-like phenotypes, strengthening the hypothesis that disruptions in mTOR-dependent protein synthesis contribute to autism pathology." (PMID 29691724, 2018). "Thus, it is not surprising that disruption or dysregulation of mTOR signaling pathway results in abnormalities of neuronal development and brain malformations causing a wide spectrum of brain disorders such as autism, seizures, and mental retardation syndromes." (PMID 29259984, 2017). "Third, through network toxicology, single-cell transcriptomics, and animal experimentation, we demonstrate that chronic PM2.5 exposure exacerbates valproic acid-induced autism-like behaviors in murine models, identifying CTNNB1, PTEN, CCR2, AKT1, and mTOR as potential core mediating genes." (PMID 41304474, 2025). "While we demonstrate that E159 ameliorates autism-like behaviors and enhances autophagy through modulation of the mTOR pathway, we did not extensively investigate the upstream signaling factors or related pathways influencing the regulation of autophagy." (PMID 39458934, 2024). "This includes a rare missense variant in MTOR, that is shared by individuals in the NAP group including individuals without an autism diagnosis." (PMID 36702863, 2023). "The PI3/AKT/mTOR pathway and its regulation by the protein known as the phosphatase and tensin homolog (PTEN), have long been known to be important players in the pathogenesis of autism." (PMID 33735311, 2021). "Meanwhile, considering the therapeutic effect of mTOR inhibitors on ameliorating autism-like symptoms, appropriate induction of FBXW7-mediated degradation of mTOR may also be beneficial for autism treatment but the effect still remains to be demonstrated." (PMID 34512273, 2021). "Given that disruption of mTOR and MAPK pathways correlates with severity in idiopathic autism, AIMTOR could even serve diagnosis purpose." (PMID 32620110, 2020). "Interestingly, Igf2 protein can reverse the core autism symptoms in the BTBR mouse model, by reducing the overactivation of mTOR pathway." (PMID 33049717, 2020). "Moreover, multiple autism-like behavioral phenotypes of Fmr1 KO mice are able to be rescued by removal of S6K1, a downstream kinase of mTOR." (PMID 31849609, 2019). "A putative autophagy impairment has been previously suggested (but not explored) in non-syndromic autism as a consequence of an increased mTOR signalling which physiologically blocks autophagy activation." (PMID 28951555, 2017). "As a result, the use of mTOR inhibition in TSC, including its use to prevent long-term morbidity, such as intellectual disability, autism, and refractory seizures, may be incorporated into clinical practice in the coming years." (PMID 28288694, 2017). "In addition to the large number of cancer cell trials employing rapamycin, the mTOR inhibitor, two clinical trials are currently focused on the use of this drug to treat TSC and autism in children." (PMID 26877878, 2016).
autism (continued). "However, systematic investigation of the MAP proteins involved in the mediation of autism-like behaviours, as well as the effect of mTOR on these proteins, is lacking." (PMID 37108467, 2023). "However, until today there are no clinical studies proving that mTOR inhibition ameliorates autism symptoms or intellectual disability in mTORopathies in human." (PMID 34828352, 2021). "Given the deleterious influence of aberrant mTOR activation in several genetic forms of autism spectrum disorders, administration of 5‐HT6 receptor antagonists as soon as adolescence might profitably be evaluated in autism." (PMID 32329240, 2020). "However, considering that the disequilibrium of the negative regulation of mTOR-signaling both by TSC1/2 and PTEN has been shown to be impaired in syndromic autisms, it is possible to claim that NF has a role in ASD-like phonotype development through its regulation of mTOR." (PMID 28420080, 2017). "We used lymphoblastoid cell lines from patients with autism of unknown etiology obtained from the AGRE collection and the SSC to test the hypothesis that dysregulated PI3K/mTOR signaling is a shared pathological mechanism, treatment target, and biomarker in autism." (PMID 26770665, 2016). "Importantly, the mTOR differences are responsible for the shared neurodevelopmental phenotypes since manipulation of the mTOR pathway with small molecules could rescue the autism NPC deficits and reproduce autism NPC phenotypes in control NPCs." (PMID 38525876, 2024). "Because BDNF/TrkB-mediated signaling pathways, including Akt-mTOR and Eps8-Rac, play a key role in the development of the cortex and in synaptic function and plasticity, altered BDNF/TrkB signaling through these pathways may be an important contributor to autism pathogenesis." (PMID 29691724, 2018). "Lack of FMRP in FXS (and in some individuals with autism), would also favor PIKE activation of mTOR and downstream Rho GTPases including Rac1 and cofilin that in turn would cause actin disassembly and myelination." (PMID 31024350, 2019). "Here, we sought to characterize mTOR and MAPK pathways in children with idiopathic autism who had no other identifiable clinical syndromes." (PMID 30705255, 2019). "A hyperactivated mTORC1–eIF4E pathway is linked to impaired synaptic plasticity in fragile X syndrome, an autistic disorder caused by lack of fragile X mental retardation protein (FMRP) due to mutation of the FMR1 gene, suggesting that downstream mTOR signaling might be causally linked to ASDs." (PMID 23533374, 2013).
triple-negative breast carcinoma (157 papers, 2013 to 2026). An invasive breast carcinoma which is negative for expression of estrogen receptor (ER), progesterone receptor (PR), and human epidermal growth factor receptor 2 (HER2). "PTEN deficiency and high PI3K and mTOR expression are linked to a poor prognosis in triple negative breast cancer patients." (PMID 38797813, 2024). "In triple-negative breast cancer, 72% of the tumours harbour phosphorylated mTOR, which is associated with shorter overall- and recurrence-free survival rates for patients with early-stage triple-negative breast cancer." (PMID 38734930, 2024). "Triple-negative breast cancer is characterized by hyperactive mTOR signaling, and this hyperactivation is attributed to loss of PTEN in triple-negative breast cancer." (PMID 35795855, 2022). "Metastasis and proliferation associated with triple-negative breast cancer were inhibited by luteolin followed by in activation of the Akt/mTOR signaling pathway with significant reversal of epithelial to mesenchymal transition." (PMID 35795855, 2022). "PI3K/Akt/mTOR pathway activation has been implicated in the cisplatin resistance of triple-negative breast cancer cells." (PMID 31645543, 2019). "Activation of the mTOR signaling pathway is associated with a more aggressive phenotype in both triple negative breast cancer and non-triple negative breast cancer." (PMID 28114374, 2017). "Loss of PTEN tumor suppressor gene is a common event in triple negative breast cancers which also leads to the activation of mTOR." (PMID 29147345, 2013). "This discrepancy may be attributed to varying expression levels of AGK protein in these two cell lines or could be associated with the heightened activation of the PI3K/AKT/mTOR signaling pathway in triple-negative breast cancer." (PMID 39594764, 2024). "An earlier study demonstrated that PRR15 inhibited Akt-mTOR activation in triple-negative breast cancer (TNBC) cells, suggesting a context-dependent role for this protein." (PMID 39929816, 2025). "For example, 3-bromo-N’-(4-hydroxybenzylidene)-4-methylbenzohydrazide derivatives as mTOR inhibitor to induce autophagic cell death and apoptosis in triple-negative breast cancer." (PMID 40651979, 2025). "For incidence, the cell proliferation is inhibited and the apoptosis is induced by LncRNA GAS5 through regulating the PI3K/Akt/mTOR signaling pathway of triple negative breast cancer." (PMID 39651612, 2024). "Meanwhile, probable antitumour effects of mTOR inhibitors have also been reported in triple-negative breast cancer." (PMID 38734930, 2024). "Western blotting revealed that phospho mTOR (pmTOR) and pS6K were expressed in the control group; high mTOR expression in human clinical triple-negative breast cancer was reproduced in our in vivo xenograft model." (PMID 38734930, 2024). "Recently, a study suggested that the AKT/mTOR signalling pathway is a major pathway in TMEM176B-dependent signalling in triple-negative breast cancer." (PMID 39001509, 2024). "Several preclinical studies have shown that a variety of dual PI3K/mTOR inhibitors are synergistic with cisplatin in triple-negative breast cancer preclinical models." (PMID 37491309, 2023). "The increase in the number of articles on triple-negative breast cancer and its relationship with mTOR signaling also represents an emerging area of research." (PMID 37637052, 2023). "Results showed that KK-CL-1 can regulate the malignant biological behaviors of triple-negative breast cancer via the MAL2/MUC1-C/PI3K/AKT/mTOR pathway." (PMID 36895039, 2023). "KK-LC-1 promotes the malignant biological behavior of triple-negative breast cancer cells via the MAL2/MUC1-C/PI3K/AKT/mTOR pathway." (PMID 36895039, 2023). "Based on these results, we can conclude that KK-LC-1 regulates the biological characteristics of triple-negative breast cancer cells through the MAL2/MUC1-C/PI3K/AKT/mTOR pathway." (PMID 36895039, 2023).
triple-negative breast carcinoma (continued). "Other study uncovered that ASF1B activated PI3K/AKT/mTOR signaling to promote cisplatin resistance in triple-negative breast cancer cells." (PMID 37693891, 2023). "It is also in agreement with the effect of fasting/FMD in forcing the activation of PI3K-AKT and mTOR-dependent escape pathways, which resulted in the death of triple negative breast cancer cells when blocked." (PMID 38136414, 2023). "In conclusion, the NAMPT-AS/POU2F2/NAMPT and NAMPT-6 AS/miR-548B-3p/NAMPT axis activate the mTOR pathway and inhibit autophagy and apoptosis-related genes, thereby promoting the survival and invasion ability of triple-negative breast cancer cells." (PMID 35813295, 2022). "An evidence-based study has shown that exercise inhibits mTOR in triple-negative breast cancer and thus plays a key role in its prevention and control." (PMID 35795855, 2022). "The PI3K–AKT–mTOR signaling pathway and mTOR inhibitors were found interlinked for the treatment of triple-negative breast cancer." (PMID 35795855, 2022). "Certain mechanisms are involved in chemoresistance of triple-negative breast cancer, and the mTOR signaling pathway is one among these mechanisms." (PMID 35795855, 2022). "In particular, its therapeutic effects can be strengthened in combination with blocking the PI3K/AKT/mTOR signaling pathway in triple-negative breast cancers." (PMID 35592706, 2022). "Recent studies have also found that luteolin significantly inhibits cancer cell proliferation and metastasis through the AKT/mTOR/MMP9 signaling pathway in androgen receptor-positive triple-negative breast cancer." (PMID 35678671, 2022). "Our previous study proved that ΔA146Ply inhibited autophagy in triple-negative breast cancer cells by activating mTOR signaling." (PMID 35538212, 2022). "For example, inhibiting ST8SIA1 can sensitize triple-negative breast cancer to chemotherapy via suppressing FAK/AKT/mTOR." (PMID 36034784, 2022). "Arnicolide D, a sesquiterpene lactone isolated from Centipeda minima, has recently been shown to exert anti-tumor activity against triple-negative breast cancer cells by inhibiting the activation of Akt/mTOR and STAT3 signaling pathways." (PMID 36428613, 2022). "Inhibition of WDR5 and mTOR cooperatively reduces translation and triple-negative breast cancer (TNBC) cell growth." (PMID 36043466, 2022). "Extracellular TIMP4 is involved in promoting the activation of the PI3K/AKT/mTOR pathway and promoting tumor metastasis, and is a prognostic and predictive marker for triple-negative breast cancer." (PMID 35847900, 2022). "Glucose metabolism also appears to underpin synergistic activities of palbociclib in combination with PI3K/mTOR inhibitors in triple-negative breast cancer." (PMID 33572972, 2021). "Telaglenastat was previously shown to decrease mTOR activity in triple-negative breast cancer cell lines, demonstrating synergy with mTOR inhibition in the latter." (PMID 34731180, 2021). "Our data demonstrate that riluzole can display synergistic anti-GBM effects with mTOR inhibitors and recent data have demonstrated that riluzole synergizes with the chemotherapeutic paclitaxel in triple-negative breast cancers." (PMID 31948038, 2020). "The present study examined the effects of tetrandrine suppressing proliferation, targeting LC3, p62, and Beclin-1 autophagy genes by inhibiting PI3K/AKT/mTOR signaling in Triple-negative breast cancer (TNBC) MDA-MB-231 cell." (PMID 30713576, 2019). "Alteration of the PI3K/AKT/mTOR pathway is a common genomic abnormality detected in triple-negative breast cancer (TNBC)." (PMID 31703728, 2019). "A triple negative breast cancer study showed that the majority of tumors (72.1%) are p-mTOR positive, whereas expression of p-mTOR is notcorrelated with tumor grade, lymph node status, and stage." (PMID 28114374, 2017).
triple-negative breast carcinoma (continued). "Mammalian target of rapamycin (mTOR) is a crucial regulator of signaling in mammalian cells, and serves as a therapeutic target for triple-negative breast cancer (TNBC)." (PMID 29162840, 2017). "Triple-negative breast cancers (TNBC) are characterized by frequent alterations in the PI3K/AKT/mTOR signaling pathway." (PMID 27374081, 2016). "A recent report has suggested therapeutically targeting phosphoinositide 3 kinase (PI3K)/mTOR signaling in conjunction with suppression of JAK2/STAT5 in certain triple-negative breast cancers." (PMID 24913037, 2014). "This is the first study that looks at an mTOR inhibitor in combination with a platinum agent in triple-negative breast cancer." (PMID 24684785, 2014). "PIK3/Akt/mTOR inhibitors used in clinical trial in triple-negative breast cancer (TNBC)." (PMID 40647529, 2025). "Furthermore, LINC00707 promotes Triple-negative breast cancer (TNBC) disease progression through the March2/mTOR pathway mediated by competitive binding to miR-423-5p." (PMID 40264452, 2025). "Relevant clinical trials have demonstrated that AKT inhibitors such as capivasertib and ipatasertib play a significant role in the PI3K/AKT/mTOR signaling pathway, both occupying important positions in the treatment of metastatic triple-negative breast cancer (TNBC)." (PMID 39469651, 2024). "Therefore, we conclude that KK-LC-1 regulates the biological characteristics of triple-negative breast cancer cells through the MAL2/MUC1-C/PI3K/AKT/mTOR pathway." (PMID 36895039, 2023). "Drugs targeting the mTOR pathway may become a promising treatment option for triple-negative breast cancer." (PMID 37637052, 2023). "Besides, Z839878730 has little tumor-killing effect on human normal mammary epithelial cells MCF10A and can inhibit the malignant biological behaviors of triple-negative breast cancer cells by MAL2/MUC1-C/PI3K/AKT/mTOR pathway." (PMID 36895039, 2023). "Based on the literature and sequencing results of this study, we speculated that KK-LC-1 may regulate the biological characteristics of triple-negative breast cancer cells through the MAL2/MUC1-C/PI3K/AKT/mTOR pathway." (PMID 36895039, 2023). "Therefore, we believe that a more complete inhibition of the PI3K and TORC1/2 pathway will increase HRD more than mTOR inhibition alone, sensitizing triple negative breast cancers to DNA damaging cisplatin and immune checkpoint inhibitors." (PMID 37491309, 2023). "The PI3K/mTOR/AKT pathway is considered a therapeutic target for triple negative breast cancers." (PMID 33924764, 2021). "SCD1 elevates migration of the triple-negative breast cancer cells by regulating PLD/mTOR axis." (PMID 34690112, 2021). "Also, it has been revealed that β-TrCP is controlled by the mammalian target of rapamycin (mTOR), the cellular metabolism regulator, with consequent downregulation of cyclin E in triple-negative breast cancer cells." (PMID 32076009, 2020). "Nobiletin shows inhibition of mTOR signaling on MDA-MB-468 triple-negative breast cancer cells." (PMID 32212785, 2020). "Triple negative breast cancers (TNBC) are often PTEN-deficient, making mTOR a compelling target." (PMID 31489111, 2019). "In light of these findings, we investigate whether tetrandrine could suppress proliferation in human triple-negative breast cancer MDA-MB-231 cell targeting autophagy and its potential association with the PTEN/PI3K/AKT/mTOR signaling pathway." (PMID 30713576, 2019). "Few triple-negative breast cancers (TNBCs) had appreciable levels of PIK3CA mutation, suggesting that individuals with TNBC may be less responsive to inhibitors of the PI3K/AKT/mTOR pathway." (PMID 30813596, 2019).